MUC1 (mucin 1, cell surface associated)
Diseases named in the same sentence as MUC1 in open-access papers (continued):
Sharing a sentence is not in itself a finding about the gene and the disease.
tumor (continued). "As cells transform to a malignant phenotype, MUC1 is overexpressed and aberrantly glycosylated, known as tumor-associated form of MUC1 (tMUC1), and remains as an exciting target for immunotherapy." (PMID 40861475, 2025). "In their design, the simultaneous presence of two tumor-associated cell-surface proteins, mucin 1 (MUC1) and EpCAM, triggers a dimer-like rolling circle amplification (RCA) process." (PMID 40452887, 2025). "The following search terms were used: (“TA-MUC1” OR “Tumor-associated MUC1” OR “MUC1” OR “Membrane-associated MUC1” OR “MA-MUC”) AND (“case report” OR “case series”) AND (“cancer” OR “carcinoma” OR “adenocarcinoma” OR “neoplasm”)." (PMID 41322748, 2025). "TG4010 is a recombinant modified bovine pox virus suspension capable of encoding MUC1 tumor related antibodies and interleukin-2 (IL-2)." (PMID 39179939, 2025). "Tumor-associated MUC1 differs from the form expressed in normal cells, both in its biochemical properties and its cellular distribution." (PMID 40443562, 2025). "In preclinical models, a chemically defined synthetic MUC1 glycopeptide vaccine directed at tumor-associated epitopes such as sTn elicited strong Th1-biased responses and activated cytotoxic T cells in murine PDAC." (PMID 41228299, 2025). "MUC1, a membrane-bound mucin, is the most extensively studied tumor-associated mucin due to its role in cancers of glandular epithelial origin." (PMID 39791742, 2025). "Preclinical studies targeting tumor-associated antigens such as MUC1 and HER2 have demonstrated promising anti-improvement activity by adoptive T cell therapy." (PMID 40264788, 2025). "Data are derived from a subset of the 73 tumor-associated MUC1 (TA-MUC1)–positive cases for which co-existing biomarker results were explicitly reported." (PMID 41322748, 2025). "Expression of the secreted form of MUC1, also known as soluble MUC1 (sMUC1), is associated with tumor burden and can be effectively targeted using the B27.29 antibody for CA27.29 epitope present on sMUC1." (PMID 40179083, 2025). "Percentages denote the proportion of each cancer type among the total tumor-associated MUC1 (TA-MUC1)-positive cases (n = 73) and represent reporting density, not prevalence." (PMID 41322748, 2025). "Tumor-associated MUC1 (TA-MUC1) refers to an aberrant form of MUC1 specifically expressed in cancer cells." (PMID 41322748, 2025). "Various nucleic acid vaccines encoding MUC1 have been developed to elicit anti-tumor response against MUC1-expressing tumors in murine models." (PMID 41012179, 2025). "Antibodies, radiopharmaceuticals, vaccines, and chimeric antigen receptor (CAR)-T cell therapies have been developed against tumor-associated MUC1." (PMID 39923010, 2025). "In tumor-associated MUC1, the VNTR region is under-glycosylated, exposing the repeat peptide chain and serving as a potential target for distinguishing between normal and tumor cells." (PMID 40363817, 2025). "Mucin-1 (MUC1) is a tumor-associated antigen that is overexpressed and abnormally glycosylated in many cancers, contributing to immune evasion and tumor progression." (PMID 40943370, 2025). "Tumor types include rare subtypes and anatomically diverse primary sites, many of which demonstrated tumor-associated MUC1 (TA-MUC1) expression as reported by immunohistochemical methods in the original articles." (PMID 41322748, 2025). "Among these, NY-ESO-1 is highly immunogenic and associated with poor prognosis, while 5T4, survivin, and MUC1 are implicated in tumor progression and reduced survival." (PMID 41007751, 2025). "MUC1 is a transmembrane mucin that is typically overexpressed in invasive carcinomas and is associated with epithelial-to-mesenchymal transition, tumor invasion, and poor prognosis." (PMID 40821195, 2025). "A glycoprotein called MUC1 is overexpressed in a large number of solid tumors and is linked to both tumor growth and a bad prognosis." (PMID 40312353, 2025).
tumor (continued). "Tumor-associated MUC1 (TA-MUC1) expression was confirmed by immunohistochemistry (IHC) in all cases listed." (PMID 41322748, 2025). "Research indicates that MUC1 expression is upregulated in TAMs, particularly in the M2 phenotype, which is associated with inflammation and tumor progression." (PMID 40655139, 2025). "CAR-T cells can be engineered to specifically target tumor-associated antigens, such as ErbB and MUC1, which are highly expressed in HNSCC." (PMID 40312353, 2025). "A study involving a cohort of 36 ccRCC patients showed that tumors expressing high levels of MUC1 are characterized by an altered metabolism, high M2 tumor-associated macrophage (TAM) response, low immune infiltration, and low expression of PD-L1." (PMID 38254882, 2024). "In this review, we will focus on the interactions between tumor-associated MUC1 (cell-surface mucin) and Siglecs (sialic-acid-binding lectins)." (PMID 38611013, 2024). "Due to the abnormally high expression of MUC1 in tumor cells and the loss of cell polarity, MUC1 is spread over the entire cell surface and can be detected in the blood as small fragments under the hydrolysis of various enzymes." (PMID 39491020, 2024). "Carbohydrate-binding proteins, lectins, are the main binding partners of tumor-associated carbohydrate antigens (TACAs) of MUC1 on the cell surface." (PMID 38611013, 2024). "There are a number of MUC1-associated tumor vaccines have been proven effective in the treatment of metastatic CRPC (mCRPC)." (PMID 39491020, 2024). "The interaction of tumor-associated MUC1 sialylated glycans with Siglecs via ITIM motifs decreases antitumor immunity." (PMID 38611013, 2024). "Our findings reveal a significant positive correlation between ST6GALNAC1, an enzyme implicated in the synthesis of tumor-associated glycans, and MUC1, a mucin glycoprotein frequently dysregulated in cancer." (PMID 38997719, 2024). "The elevated expression rate of MUC1 is linked with the stage of the tumor and the amount of remaining tumor tissue after surgery." (PMID 38540735, 2024). "Other studies have shown that MUC1 is heavily sialylated and mice deficient in MUC1 resist tumor formation while primary tumor xenografts that overexpress MUC1 grow and metastasize more aggressively." (PMID 39628991, 2024). "MUC1 is the second-most promising target for cancer immunotherapy among the top 75 tumor-associated antigens due to its widespread distribution on both primary tumors and metastases, including cancer stem cells." (PMID 38611013, 2024). "MUC1 is a transmembrane glycoprotein which is aberrantly expressed in tumors and thus acts as a tumor-associated antigen in various types of cancer." (PMID 38910324, 2024). "Siglecs play a key role in mediating cell–cell interactions via the recognition of different sialylated glycoconjugates, including tumor-associated MUC1, which can lead to the activation or inhibition of the immune response." (PMID 38611013, 2024). "In our systematic study, MUC1 was manifested to be associated with tumor progression, and high MUC1 expression was positively correlated with vascular invasion, lymph metastasis, and lymphatic invasion." (PMID 39886661, 2024). "Undoubtedly, MUC1 causes inflammation to turn into cancer, increases treatment resistance, enhances tumor spread, and is involved in cancer progression." (PMID 38540735, 2024). "Many of theseDEPs have been suggested as potential clinical prognostic markers,due to their functional association with tumor growth and progression.32−37 We found upregulation of MUC1 and RAP1B in LUAD pEV samples comparedwith the MM pEV samples." (PMID 39141927, 2024). "Previous studies have reported that the glycosyltransferase ST6GALNAC1 can promote the synthesis of various tumor-associated MUC1-sialyl-Tn glycans." (PMID 38997719, 2024). "The use of multiple cell lines and MUC1 antigen variants helped to tease out different factors that most strongly influence antibody efficacy in eliminating target tumor cells." (PMID 39449327, 2024).
tumor (continued). "MUC1, a membrane-bound mucin, is the most studied tumor mucin, as it is closely associated with the development of cancers of glandular epithelial origin." (PMID 38727261, 2024). "The structure of tumor-associated MUC1 was significantly altered compared to that of normal cell surface MUC1." (PMID 38164273, 2024). "Recent evidence points to the importance of tumor-associated carbohydrates in MUC1 antibody binding and for generating a robust immune response in vaccine candidates." (PMID 38611013, 2024). "During chronic inflammation and carcinogenesis, M2 macrophages induce the expression of ST6GALNAC1, thereby promoting abnormal glycosylation of MUC1, leading to the formation of tumor-associated sialyl-Tn (sTn) O-glycans, exacerbating disease progression." (PMID 38997719, 2024). "In CMTs, MUC-1 expression was also associated with tumor invasion and the presence of metastases, which had prognostic significance." (PMID 38474142, 2024). "The expression of T, sTn on tumor mucins such as MUC1 which plays as various selectins of ligands, caused by abnormal glycosylation promotes metastasis and spread." (PMID 38699634, 2024). "The potential of thismodified glycopeptide as a mimic of a tumor-associated MUC1 antigentriggered us to test it in vivo, which proved that antibodies generatedin mice with this synthetic antigen recognized human cancer cell lineswith high selectivity." (PMID 38274250, 2024). "MUC1 is known as a tumor-associated molecule in many cancers due to overexpression and abnormal glycolysis." (PMID 38463926, 2024). "MUC1 was associated with gender, Lauren classification, depth of tumor invasion, TNM, vascular invasion, lymph metastasis, and lymphatic invasion, WHO grade, as well as the 5-year survival rate." (PMID 39886661, 2024). "A different mechanism of MUC1 is associated with the regulation of tumor cell proliferation and apoptosis, which is connected to regulating multiple tumor cell proliferation/apoptosis pathways." (PMID 38540735, 2024). "Tumor-associated MUC1 (TA-MUC1) is a tumor-specific transmembrane glycoprotein whose glycosylation is altered due to the deregulation of several sialyltransferases in tumor cells." (PMID 39432076, 2024). "While, MUC1 deficiency has been shown to suppress inflammation, inhibit tumor progression, increase the abundance of CD8 T-lymphocytes, and decrease the abundance of macrophages in colon tumors." (PMID 38699634, 2024). "Studies have shown that in tumor patients, the loss of epithelial cell polarity results in significant underglycosylation, leading to the overexpression of MUC1." (PMID 39491020, 2024). "For instance, numerous studies have shown that interactions of sialylated glycans of tumor-associated MUC1 (TA MUC1) with the sialic-acid-binding lectins promote tumor immune escape, ultimately affecting the body’s antitumor immunity." (PMID 38611013, 2024). "We developed GT-00AxIL15 as first-in-class IL-15-based immunocytokine targeting a tumor-associated, glycosylated epitope of MUC1 (TA-MUC1) to optimize tumor accumulation, efficacy, safety and half-life of IL-15 compared to untargeted therapeutics." (PMID 38338686, 2024). "Studies have indicated that, overexpression of MUC1 is significantly associated with tumor angiogenesis and adverse patient outcomes in PCa." (PMID 39491020, 2024). "Based on this method, DNA tetrahedra combined with multiple aptamers were conceived for quantitatively detecting tumor-associated mucin-1 (MUC-1) protein." (PMID 36992023, 2023). "Gatipotuzumab (also known as PankoMab-GEXTM or PMG) is a humanized and glyco-optimized mAb that recognizes tumor-associated MUC1 glycopeptide." (PMID 37489369, 2023). "Some studies have reported that elevated MUC1 expression is directly associated with a higher risk of invasion and poor prognosis, contributing to the angiogenesis, tumor growth, and development of metastasis." (PMID 37685842, 2023).
tumor (continued). "The red cluster is related to the “tumor microenvironment”, with keywords such as “tumor-associated macrophage”, “suppressor T cell”, “muc-1”, and “regulatory T-cell”." (PMID 36766879, 2023). "For example, truncated variants of the natural MUC1 mucin are found overexpressed in many tumor tissues." (PMID 37486039, 2023). "The vaccine comprised 6 mRNA molecules encoding for fixed tumor-associated antigens: Mucin1 (MUC1), survivin, NY-ESO-1, 5T4, MAGE-C2, and MAGE-C1, which are overexpressed in NSCLC compared to healthy tissue." (PMID 38067293, 2023). "The MEC areas were compared with the surrounding NSGs by staining with anti-MUC1 antibody, anti-sialyl-Tn antibody that is a well-known tumour-associated antigen and MAL-II." (PMID 37031283, 2023). "Abnormally high expression of MUC1 on cancer cells causes physical barriers, blocking the detection of tumor-associated antigens (TAAs) and preventing immune cells from killing tumor cells." (PMID 36738352, 2023). "Peptide-loaded DC vaccines selectively targeting tumor-associated antigens (TAAs) such as mucin 1 (MUC1), Wilms’ tumor gene 1 (WT1) and mutant K-RAS also enhance more cytotoxic lymphocyte response." (PMID 37064113, 2023). "Recent studies show that MUC1 is implicated in tumorigenesis, tumor cell movement, resistance to chemotherapeutic drugs, and stress-induced apoptosis." (PMID 37631305, 2023). "Real-Time PCR, ELISA, and Western blotting were applied to examine MUC1 expression, specific, tumor-associated antigens, enzymes taking part in their formation, Gal-3, Akt, and NF-κB." (PMID 37685842, 2023). "The present research focused on the use of a DNA vaccine targeted at one of the commonly found tumor-associated antigens, human MUC1." (PMID 36980805, 2023). "Expression of sialyl-Tn, a well-known tumour-associated glycan antigen, was also evaluated and compared with expression of MUC1." (PMID 37031283, 2023). "Malignant MUC1 is involved in multiple signaling pathways which are associated with various aspects of tumor progression." (PMID 37345016, 2023). "Tumor-associated MUC1 displays the hypo-glycosylation of core glycans, in which the long-branched glycan chains in normal tissues are truncated." (PMID 37489369, 2023). "In particular, neoplasms overexpress a hypo-glycosylated variant of MUC1, also known as tumor-specific MUC1 (tMUC1) which exposes new epitopes for the immune system." (PMID 36900394, 2023). "The overexpression of MUC1 is associated with tumor progression and decreased overall survival in patients with various tumors." (PMID 37489369, 2023). "As suggested by the GSEA results, MUC1 is implicated in other additional characteristics of tumor biology, including induction of angiogenesis and immune cell infiltrate modulation." (PMID 36902242, 2023). "A cancer vaccine known as the BLP25 liposome vaccine (L-BLP25) targets the exposed core peptide of MUC1 tumor-associated antigen." (PMID 37631305, 2023). "Several studies have indicated that MUC1 plays a critical role in the transcriptional regulation of genes associated with tumor invasion, metastasis, angiogenesis, proliferation, apoptosis, drug resistance, inflammation, and immune regulation." (PMID 35568869, 2022). "Obtained results show strong humoral and cellular response of vaccinated mice to chimeric VLPs presenting tumour-associated MUC1 antigen and the VP1 platform itself." (PMID 35351156, 2022). "In concordance with our in vitro findings, MUC1 expression in single SCLC tumor cells was significantly associated with activation of the HALLMARK MYC TARGETS V1 gene signature." (PMID 35612556, 2022). "One of the most promising features of MUC1 is its cancer-associated antigenic function due to the presence of tumour-specific antigen epitopes and increased expression in variety of tumour cells." (PMID 35351156, 2022).
tumor (continued). "As a result, a MUC1 vaccine equipped with covalently linked divalent mannose ligands and a tumor-related huMUC1 vaccine combined with the tetanus toxoid are promising anti-BRCA vaccines." (PMID 35883508, 2022). "In malignant cells, however, tumor-associated MUC1 (tMUC1) differs from MUC1 that expressed on normal cell in its structure and distribution." (PMID 36457849, 2022). "MUC1 exposes tumor-associated carbohydrate antigens (TACAs) like the Tn antigen (single N-acetylgalactosamine α O-linked)." (PMID 35454775, 2022). "The expression of MUC1 in normal epithelial cells is limited to the apical surface, but covers the entire surface in many tumor cells due to the loss of polarity, thus increasing the opportunity to contact with external substances." (PMID 35970845, 2022). "Some of the most important heavily glycosylated tumor-associated antigens studied today are Mucins, and of those MUC1 is arguably the most heavily researched." (PMID 35432351, 2022). "During the past few decades, tumor-associated antigens such as MUC1 glycopeptide, glycolipids and Globo-H have been used as effective anti-tumor vaccine epitopes." (PMID 35877485, 2022). "The three tumor-associated transcripts used here were MUC1 (mucin 1), HER2, and GA733-2—the messenger ribonucleic acid (mRNA) of the EpCAM." (PMID 35453519, 2022). "In this report we introduce tumour-associated MUC1 epitope (PDTRPAPGSTAPPAHGVTSA) sequence into NoV VP1 gene to produce MUC1 chimeric VLPs." (PMID 35351156, 2022). "The expression of MUC1 was positively correlated with cancer stem cell markers such as CD24, PSCA and TM4SF1, which indicated that the high expression of MUC1 in malignant cells was associated with tumor proliferation." (PMID 36104333, 2022). "As a result, tumor cells were predisposed to MUC1-CAR-T cells by the higher expression level of the target antigen, which led to efficient tumor cell killing." (PMID 36419058, 2022). "Tumor-associated antigen mucin 1 (MUC1) is overexpressed on many human epithelial tumor tissues, such as breast, ovarian, and prostate carcinomas, which makes it an attractive target for tumor immunotherapy." (PMID 35371101, 2022). "Mucin 1 (MUC1) is a membrane-associated glycoprotein overexpressed in many different kinds of epithelial tumor tissues, making it an attractive target for tumor immunotherapy." (PMID 36499455, 2022). "In cancer, tumor-associated Muc1 loses its apical restriction, becomes aberrantly glycosylated, and becomes overexpressed in 46–98% of CRCs, depending on the stage." (PMID 35053365, 2022). "The tumour-associated form of MUC1 is hypoglycosylated in contrast with its heavily glycosylated normal form in healthy, non-cancerous environment which has five potential O-glycosylation sites (because of its PDTRP motif)." (PMID 35351156, 2022). "Qβ VLPs presenting tumor-associated MUC1 have been developed, and their efficacy as an anti-cancer vaccine have been demonstrated (MUC1-Qβ VLPs)." (PMID 36714624, 2022). "Due to the high glycosylation profile of MUC1 and aberrant glycosylation profile of tumour-associated MUC1 it is crucial to choose an expression system supporting the mammalian type of post-translational modification." (PMID 35351156, 2022). "Here, for the first time to our knowledge, we present the bioengineered nanostructures based on the Norovirus (NoV) VLPs that present multiple copies of tumour-associated form of MUC1 epitope on their surface." (PMID 35351156, 2022). "Studies have shown that high expression of MUC1 promotes tumor cell proliferation and metastasis, and its expression is proportional to tumor malignancy and is associated with poor prognosis in patients." (PMID 35784721, 2022). "Presented results show successful expression of the chimeric MUC1 particles in L. tarentolae that leads to the production of high titers of tumour-associated MUC1 antibodies." (PMID 35351156, 2022).